CXCL10 (C-X-C motif chemokine ligand 10)
Diseases named in the same sentence as CXCL10 in open-access papers (continued):
Sharing a sentence is not in itself a finding about the gene and the disease.
asthma (continued). "As well, the efficacy of the thiazolidinediones in reducing asthmatic and non-asthmatic ASMC CXCL10 release has been demonstrated, even under inflammatory conditions where current asthma therapies were ineffective or enhanced release." (PMID 23034049, 2012). "In this study the inflammatory conditions under which current asthma therapies down-regulate production of the mast cell chemoattractant CXCL10 by ASMC from people with and without asthma were established." (PMID 23034049, 2012). "The serum levels of TNF‐α (p = 0.025), IFN‐γ (p = 0.011), CCL22 (p = 0.022), IL‐12p70 (p = 0.021), CXCL10 (p = 0.028), CCL2 (p = 0.028), CCL13 (p = 0.024), IL‐4 (p = 0.026), IL‐13 (p = 0.024), and CCL11 (p = 0.028) were found to be downregulated in stable asthma when compared to acute asthma." (PMID 39508721, 2024). "However, our findings indicated that CXCL10 production by lung epithelial cells was not concomitant with IFN-γ elevation, supporting the previous study showing CXCL10 expression is partially independent of IFN-γ in an OVA-challenged asthma mouse model." (PMID 37029363, 2023). "A previous study has identified that ASMCs under the asthma conditions induce the migration of MCs through releasing adenosine triphosphate (ATP), the effect of which can be mimicked by ADP that produces results similar to or greater than those obtained using ATP, and CXCL10." (PMID 34291079, 2021). "While 50% of asthma patients who are not responsive to corticosteroid treatments have elevated levels of Cxcl10, a study suggested that Cxcl10 could reduce steroid resistance." (PMID 34093515, 2021). "Interestingly CXCL10 production induced by IFNγ or cytomix is also not inhibited by current asthma therapies such as fluticasone and/or salmeterol, whereas IL-1β- and TNF-α-induced release is markedly reduced by these agents." (PMID 24648846, 2014). "Asthma appeared to modify RV-induced secretion of CXCL10 and TNFα in that RV infection stimulated increased secretion of these cytokines only in subjects without asthma (asthma × RV interaction p values: CXCL10, 0.003; TNFα, 0.0003)." (PMID 24219422, 2013). "Therefore, effector cells including T cells, NK cells, and DCs may be recruited via MC‐derived chemokines including CXCL10 and CCL5 during HRV infection; however, whether inflammatory cell recruitment would result in viral clearance or contribute to asthma pathology requires further investigation." (PMID 28008678, 2017). "In non-diabetic individuals with asthma, MCP-1 levels correlated with IL-1β, IL-1RA, MDC/CCL-22, IP-10/CXCL-10, GM-CSF, FGF-2, PDGF-AA, PDGF-BB, and HbA1c." (PMID 27709105, 2015). "In this study we have demonstrated that MC products released from granules soon after cell activation, or newly synthesized and then released later, differentially modulated levels of CXCL10 released by ASM cells from donors with and without asthma." (PMID 24648846, 2014). "The levels of CXCL10 released by untreated ASM cells from people with and without asthma were very low." (PMID 24648846, 2014). "Neither tryptase (0.2, 1, or 5 nM) nor the vehicle (heparin 50 μM) induced CXCL10 release from ASM cells from people with and without asthma." (PMID 24648846, 2014). "This is the first study to examine the effects of MC products on CXCL10 production by ASM cells from people with and without asthma." (PMID 24648846, 2014). "The aims of this study were to investigate the individual and combined effects of the GC fluticasone with the LABA salmeterol or the thiazolidinedione ciglitazone, on cytokine-induced CXCL10 release by ASMC from people with and without asthma." (PMID 23034049, 2012). "TNF-α- or IL-1β-induced CXCL10 release by ASMC from people with and without asthma was strongly inhibited by GC and LABA treatment in this study." (PMID 23034049, 2012). "Thus, the aims of this study were to investigate the effects of MC products on CXCL10 production by ASM cells from people with and without asthma." (PMID 24648846, 2014).
asthma (continued). "Thus the effects of glucocorticoids (fluticasone, budesonide), long-acting β2-agonists (salmeterol, formoterol) and thiazolidinediones (ciglitazone, rosiglitazone) on CXCL10 production by ASM cells (ASMC) from people with and without asthma were investigated in vitro." (PMID 23034049, 2012).
diabetes (99 papers, 2007 to 2026). "Second, increased CXCL10 levels are frequently detected in patients with overt type 1 and type 2 diabetes and in subjects at risk of development of diabetes just before its onset." (PMID 36059840, 2022). "Significant increases in MIG/CXCL6 and IP-10/CXCL10 have been suggested as a causative agent of diabetes in mammals." (PMID 35153741, 2021). "The study also confirmed the correlation of tradition risk factor with CXCL10, as mean serum levels of CXCL10 in patients with hypertension, dyslipidemia, obesity, diabetes and smoking were significantly higher as compared to the control group." (PMID 30210493, 2018). "We observed associations between self-reported diabetes and the chemokines previously reported in the literature, including CXCL10 and interleukin-8 (IL-8), as well as identified a number of novel associations such as: CCL19, CCL20, CCL21, CXCL6, and CXCL11." (PMID 28753646, 2017). "Increased levels of CCL4 in Yakutia may be associated with a lower incidence of diabetes and a higher incidence of nervous system diseases, and increased levels of CXCL10 in Yakutia, with a higher incidence of respiratory diseases." (PMID 39769502, 2024). "This might be the case for Cxcl10 that encodes a chemokine expressed by beta cells, that attracts T lymphocytes and thus participates to diabetes onset and progression." (PMID 36611907, 2022). "These clustered 7 proteins also showed some weak-to-moderate positive correlations with the remaining 11 proteins, including 3 proteins that were inversely associated with diabetes (CD6, CXCL10, and TWEAK)." (PMID 38643166, 2024). "In diabetes, a dual luciferase reporter gene assay verified that miR-16-5p and CXCL10 interact and that both are involved in the process of apoptosis." (PMID 38445373, 2024). "In diabetes, pancreatic beta cells in a pro-inflammatory environment release EVs with CXCL10 on the surface, which induces failure of neighbouring beta cells through activation of the CXCL10/CXCR3 axis." (PMID 37686134, 2023). "Blocking CXCL10 reduces diabetes and splenocytes from diabetic NOD mice were less efficient at transferring diabetes into IFN-γ or IFNGR-deficient NOD mice due to impaired homing of T cells into islets." (PMID 37293126, 2023). "Elevated concentrations of IP10 (CXCL10) have been reported in type 2 diabetes, and are associated with higher diabetes risk." (PMID 35840765, 2022). "CXCL10 is thought to be a key chemoattractant in diabetes pathogenesis and has been found elevated at early stages of T1D in rodent and human studies, including in serum from individuals with newly diagnosed T1D." (PMID 34828301, 2021). "CXCL10 is also a pro‐inflammatory biomarker identified for multiple diseases, such as cancer, diabetes, cardiovascular, and infectious diseases." (PMID 34212132, 2021). "Mice lacking CXCR3 and infected with lymphocytic choriomeningitis virus-WE strain (LCMV-WE), an established model to study T1D, exhibited a delay in insulitis, while overexpressing CXCL10 in mouse islets accelerated LCMV-induced diabetes." (PMID 34691077, 2021). "CXCL-10/IP-10 concentrations were higher in Diabetes Group, intermediate in Group B, and lower in Group A. These data were statistically significant between Groups A and B (p = 0.02) and Groups A and C (p = 0.0001)." (PMID 32038662, 2020). "CXCR3 silencing leads to abolished anti-fibrotic effects from CXCL10, indicating that CXCL10 abundance is necessary to prevent fibrosis and the progression of DN in experimental diabetes." (PMID 32365893, 2020). "CXCL10 is closely associated with autoimmune-mediated diabetes, and the expression of the CXCL10 gene increases prior to onset of diabetes in NOD mice, a rodent model of autoimmunity." (PMID 26018641, 2015). "We also noted elevated levels of CXCL10 (IP-10) in the diabetic mice compared to the control mice, further indicating prolonged proinflammatory conditions during diabetes." (PMID 23533683, 2013).
diabetes (continued). "In the diabetic mice, we observed aberrant and significantly elevated levels of IL-1α, IL-1β, IL-6 and CXCL10 compared to the control group, which indicated prolonged proinflammatory conditions during diabetes." (PMID 23533683, 2013). "In a virus-induced TID model, blockade of CXCL10 (IP-10) prevents diabetes development by impeding expansion of autoreactive T cells and their migration into the pancreas." (PMID 18793419, 2008). "Previous work has proposed CXCL-9 and CXCL-10 as potential biomarkers of type 1 diabetes mellitus." (PMID 38742118, 2024). "The urinary levels of CXCL10 increase significantly in individuals with diabetes." (PMID 38542060, 2024). "In diabetes, pancreatic beta cells in a pro-inflammatory environment release EVs with CXCL10 on the surface, which induce failure of neighboring beta cells through activation of the CXCL10/CXCR3 axis." (PMID 38379702, 2024). "C-X-C motif chemokine 10 (CXCL10) is a small cytokine belonging to the CXC chemokine family that is correlated and responsible for the greater susceptibility of patients with severe portal hypertension, diabetes, obesity, and lung cancer." (PMID 36685671, 2023). "CCL2, CCL8, and CXCL10 have also been demonstrated to play a role in the development of diabetes." (PMID 36299624, 2022). "Although the changes in CXCR3 expression were only significant in one of the newly diagnosed cohorts, they showed the same downward trend that we observed in the long-standing diabetes cohorts, along with the same significant increases in serum levels of CXCL10 and CXCL11." (PMID 29881878, 2018). "Our findings are concordant with clinical/laboratory data that demonstrated a suppression in angiogenesis due to an increase in angiogenic inhibitors in patients with diabetes combined with an increase in CXCL10 and TIMP1 expression at the transcriptional and protein levels." (PMID 26861446, 2016). "Thus, blocking type I IFN signaling during diabetes partially but significantly restored the levels of IL-1α, IL-1β, IL-6, and CXCL10." (PMID 23533683, 2013). "Interestingly, blocking type I IFN signaling during diabetes partially restored the levels of CXCL10." (PMID 23533683, 2013). "In this regard, it was shown that, after the treatment of CXCL10 DNA vaccination (pCAGGS-CXCL10), the spontaneous diabetic mice could induce the production of anti-CXCL10 Ab and inhibit the occurrence of spontaneous diabetes in vivo." (PMID 35242125, 2021). "CCL2 and CXCL10 attract macrophages, and may contribute to the recruitment of immune cells during the early stages of insulitis, as suggested by the observation that transgenic expression of CCL2 in beta cells causes insulitis and diabetes." (PMID 22412385, 2012). "In individuals with diabetes, circulating C-X-C motif ligands (CXCL9 and CXCL10) levels are significantly elevated, which have been associated with the recruitment of T helper cells 1 and 17 into the kidney." (PMID 38542060, 2024). "Glucagon–CXCL10 colocalization, was greater than insulin–CXCL10 colocalization in new-onset diabetic NOD mice, and further increases on diabetes onset." (PMID 38979061, 2024). "For example, administration of a CXCL10-neutralizing antibody following aCD3 treatment resulted in reduced CD8+ T cell infiltration into pancreatic islets and increased diabetes remission compared to aCD3 monotherapy in preclinical type 1 diabetes models." (PMID 37458220, 2023). "In multivariate logistic regression models with SHR >1.14 as the dependent variable, log IL-10, IL-10/TNF-α ratio, log CXCL10, and log IFN-γ were separately included together with age, sex, presence of diabetes, CRP, and severity of disease as covariates." (PMID 36059840, 2022). "This is in good agreement with findings in diabetes-prone NOD mice, where increased expression of CCL2, CXCL10 and other chemokines/cytokines are observed in the pre-diabetic period." (PMID 22412385, 2012).
diabetes (continued). "After adjusting for age, sex, smoking, arterial hypertension, diabetes mellitus, obesity, dyslipidemia, coronary artery disease and congestive HF, the standardized log (FIB-4 index) is significant relativity CXCL10 (β-estimate 0.160 with 95% CI:0.127–0.194, p < 0.0001)." (PMID 40264510, 2025). "Patients with diabetes and hypertension showed elevated IL-6, CRP, and CXCL-10 (p < 0.001)." (PMID 35967091, 2022). "A prospective study of the general population with and without diabetes from the KORA cohort showed that serum levels of CCL7, CXCL10, and DNER partly mediated the association between obesity and PN." (PMID 35651981, 2022). "Differentially regulated genes not overlapping with ERCB data also reflected diabetes-associated changes, such as extracellular matrix (ANGPTL4, TNN, DPT, COL9A2) or gestational diabetes (LAT2, HP, CXCL10, CD86, CD68, REN, SLC2A3, VCAM1)." (PMID 33923831, 2021). "However, in the diabetes RIP-LCMV glycoprotein mouse model, it has been shown that specific targeting of GAG-trapped CXCL10 was less effective in reversing hyperglycemia than antibodies directed against the free chemokine." (PMID 31824304, 2019). "In addition to CXCL10 and CXCL11, our analysis of serum chemokines and cytokines revealed elevated concentrations of BAFF in individuals with long-standing diabetes." (PMID 29881878, 2018). "Serum level of CXCL10 was found to be elevated in fracture patients with type 2 diabetes mellitus compared to patients with diabetes without fracture and normal patient with fracture." (PMID 28303118, 2017). "The best model for predicting liver inflammation (METAVIR grade 2–3) comprised CXCL10, TIMP1 and APRI (AUROC = 0.798); whereas the best model for predicting steatohepatitis incorporated IL8, ADIPOQ, MMP2, MMP7, age, BMI and diabetes (AUROC = 0.857)." (PMID 27861569, 2016). "We first found that diabetes induction was accompanied by an elevation in the plasma levels of reactive oxygen species (ROS), hydroperoxide, malondialdehyde (MDN), and the proinflammatory cytokines IL-1α, IL-1β, IL-6, and CXCL10." (PMID 23533683, 2013). "In line with this hypothesis, administration of an antibody neutralizing CXCL10 following aCD3 treatment resulted in reduced CD8+ T-cell infiltration into pancreatic islets and increased remission of diabetes compared to aCD3 monotherapy in preclinical disease models." (PMID 37458220, 2023). "Our data revealed significantly increased plasma CXCL10 concentrations in patients with obesity compared with healthy donors, which was even significantly elevated in patients with an additional OSAS but not influenced by the individual diabetes status." (PMID 38175171, 2024).
glioma (94 papers, 2007 to 2026). A benign or malignant brain and spinal cord tumor that arises from glial cells (astrocytes, oligodendrocytes, ependymal cells). "Chemokines associated with T cell trafficking (CCL3, CCL5, CXCL9, and CXCL10) were all upregulated in KR158B glioma tissue compared to naïve tissue." (PMID 39272914, 2024). "Therefore, CXCL10 production is hampered in IDH1-mutated glioma cells in a STAT1-dependent manner, seemingly correlating with reduced tumor infiltration." (PMID 35385679, 2022). "IDH1/2 mutations reduced the release of CXCL10 that attract the accumulation of CTLs, and increased the production of PD-L1, hinting the involvement of glioma cell metabolism in the dysfunction of CTLs." (PMID 34211978, 2021). "Our study evaluated the mRNA expression of CXCL10 using public data from The Cancer Genome Atlas (TCGA) and the GTEx database, as well as 24 pairs of glioma tissue samples." (PMID 38461458, 2024). "Analysis of the TCGA database revealed a significant increase in CXCL10 mRNA expression correlating with higher WHO glioma grades." (PMID 38461458, 2024). "We observed that CXCL10 expression correlates positively with glioma malignancy and inversely with patient prognosis, highlighting its potential as a glioblastoma treatment target." (PMID 38461458, 2024). "In our current study, we demonstrated high CXCL10 expression in glioma, negatively correlating with patient prognosis." (PMID 38461458, 2024). "Overall, we have demonstrated that CXCL10 functions as an oncogene and identified it as a potential therapeutic target for calycosin in glioma treatment." (PMID 38461458, 2024). "In gliomas, CXCL10 expression is mainly regulated by the type-I IFN pathway, particularly influenced by poly(I)-induced IFN autocrine and paracrine signaling through IFNAR1 activation." (PMID 39429695, 2024). "In gliomas with a mutation of the isocitrate dehydrogenase gene (IDH-mutation), decreased expression of the T cell-attracting chemokines CXCL9 and CXCL10 was found, resulting in reduced migration of CD8+ T cells to tumors in vitro." (PMID 38275375, 2023). "Some studies have shown that the expression of CXCL10 is up-regulated in gliomas and increases with the increase of malignant degree of gliomas, and promotes early tumor growth by increasing tumor neovascularization." (PMID 37726303, 2023). "The local stimulation of CXCL10 allowed the precise recruitment of activated CD8+ T cells to induce the apoptosis of metastasizing glioma cells in vitro (GL261 cell line) and in vivo." (PMID 38104126, 2023). "Fusion protein therapies induce CXCL10 expression for T cell infiltration, inhibiting glioma growth and improving survival." (PMID 38104126, 2023). "It reduces CXCR3 receptor and CXCL10 expression on the tumor cells while increasing CXCL10 expression in the glioma microenvironment." (PMID 38104126, 2023). "In vitro application of the oncometabolite α-hydroxyglutarate (α-HG), typical of IDH-mutated gliomas, confirmed its direct effect on reduced expression of the chemokines CXCL9 and CXCL10 and thus on reduced migration of CD8+ T cells." (PMID 38275375, 2023). "An important observation is the description of a subset of TAMs with CD169+ expression in human and mouse gliomas that produce pro-inflammatory cytokines such as CXCL10 and CCL5, leading to the accumulation of T cells and NK cells." (PMID 38275375, 2023). "CXCL10 showed tumor-promoting properties and the manifestation of chemokine receptor/ligand pair CXCR3/CXCL10 had an essential role in the proliferation of glioma." (PMID 36091778, 2022). "Elevated levels of Cxcl10 mRNAs are thus consistent with the observed reduction in miR-21 KO glioma cell proliferation." (PMID 35572197, 2022). "IDH-mutated tumors were found to express less IFN-γ inducible chemokines such as CXCL10, which was further confirmed by the introduction of IDH1 mutation which decreased CXCL10 expression and reduced the number of T cells in a glioma mouse model." (PMID 35203421, 2022).